IL6 (interleukin 6)
Diseases named in the same sentence as IL6 in open-access papers (continued):
Sharing a sentence is not in itself a finding about the gene and the disease.
colitis (continued). "It has been reported that proinflammatory cytokines such as IL6 and TNF-α and inflammatory mediators such as NO rise in primary stages of TNBS-induced colitis in rats." (PMID 33505492, 2021). "Colitis also induced a significant increase in the colonic levels of the pro-inflammatory cytokines TNF-α, IFN-γ, IL-1β, IL-6 and IL-17 measured via CBA." (PMID 34248633, 2021). "The authors further verified that the administration of micheliolide strongly inhibited IL-6, TNF-α, and IL-1β expression in a murine model of DSS-induced colitis." (PMID 34208907, 2021). "We detected a notable increase in serum IL-6 and KC in mice treated with DSS for 5–7 days, supporting the idea that acute colitis promotes a systemic inflammatory response." (PMID 34758843, 2021). "Animals with colitis administered with RL-FNPs expressively reduced the expression of TNF-α, IL-1β, IL-6, and IL-12, with effectiveness comparable to that of the dexamethasone group, with the exception of IL-12." (PMID 33499333, 2021). "By contrast, production of IL-6 was downregulated in macrophages after resveratrol treatment whereas in mice with Dextran Sodium Sulfate (DSS)-induced colitis resveratrol decreased IL-6 release but increased TNF-α release." (PMID 33935732, 2021). "The concentrations of proinflammatory cytokines IL-1β, IL-6, and CCL-2 in the colonic tissues of colitis mice decreased significantly, while anti-inflammatory cytokines IL-33 and IL-10 increased significantly." (PMID 34567209, 2021). "Exposure to EC significantly induced colitis in mice: it induced colon shortening, myeloperoxidase activity, and TNF-α, IL-1β, and IL-6 expression in the colon." (PMID 33731795, 2021). "It has been reported earlier that, in colitis, increased levels of cytokines such as TNF-α and IL-6 have a significant contribution to body weight reduction by the release of appetite suppressive neuropeptides." (PMID 33802553, 2021). "After mice with TNBS-induced colitis were treated by intragastric administration of ginsenoside Rb1, the levels of pro-inflammatory cytokines (TNF-α, IL-1β, and IL-6) declined, while the levels of anti-inflammatory cytokines (IL-10) increased." (PMID 33462754, 2021). "The mRNA expression levels of pro-inflammatory cytokines, including IL-1B, IL-17, and IL-6, were significantly downregulated in the 3D-TMSC-treated group when compared with those in the colitis control group (P = 0.001, P = 0.001, and P = 0.024, respectively)." (PMID 34599237, 2021). "The colitis model group expressed significantly higher levels of colonic TNF-α, IL-1β, and IL-6, and lower levels of IL-10 compared with the control group." (PMID 35071260, 2021). "The mRNA expression of IL-1β, IL-18, IL-6, TNF-α, IFN-γ, ICAM-1, and VCAM-1 was markedly (all p < 0.01) up-regulated in DSS-induced colitis group, while the IL-10 expression was significantly (p < 0.01) down-regulated." (PMID 33859564, 2021). "This was accompanied by lower production of colonic inflammatory cytokines (i.e., Nlrp3, IL-1β, IL-6, Tnf-α and Ccl2, REV-ERBα target genes) in colitis mice dosed at ZT10." (PMID 34393786, 2021). "Several pro-inflammatory cytokines, e.g., TNFα, IL-1β, IL-6, and IL-17A, are known to be involved in DSS-induced colitis." (PMID 33871822, 2021). "In the colitis rat model, aloin can reduce the inflammatory injury of rats by down-regulating the expression of TNF-α and IL-6." (PMID 34769051, 2021). "In other colitis mouse models, TNF-α, IL-6, and IL-1β in serum and colon were reduced after administering doenjang, fermented soybean paste, and isoflavones such as daidzein and genistein, which are bioactive compounds of soybeans." (PMID 34066160, 2021). "Results demonstrated that feeding BLIDF markedly mitigated DSS-induced acute colitis symptoms and down-regulated IL-6, TNF-α, and IL-1β levels in the colon and serum of colitis mice." (PMID 33807544, 2021).
colitis (continued). "IL-6 and TNF-α gene expression was upregulated in most intestinal inflammations such as IBD, colitis, and necrotizing enterocolitis." (PMID 34646877, 2021). "The results showed that ARS treatment notably downregulated the mRNA and protein expression of IL-1β, IL-6, TNF-α, and the protein ratio of p-p65/p65 and p-IκBα/IκBα in colon tissues in colitis mice (p < 0.01)." (PMID 33767628, 2021). "Serum GSH levels decreased, while serum TNF-α, IL-6, and MDA increased significantly in the acetic acid-induced colitis group compared to the normal control." (PMID 33441125, 2021). "It was found that serum TNF-α, IL-6, IL-18 and IL-1β levels in DSS induced colitis mice model was significantly higher than those in the control normal group." (PMID 34628369, 2021). "Using ELISA, we also found the expression levels of the pro-inflammatory cytokines TNF-α, IL-6, IFN-γ, and IL-1β were increased in PBLDIEC−/− mice versus WT mice with DSS-induced colitis." (PMID 34059646, 2021). "7-day long administration of 2.5% DSS to HFD-fed mice resulted in a distinct colitis phenotype at week 16th confirmed by an increase of DAI, IL-6 mRNA expression and MPO activity." (PMID 34380504, 2021). "The proinflammatory cytokine levels of IL-1β, TNF-α, IL-6, and IFN-γ were increased whereas the anti-inflammatory cytokine IL-10 was decreased in colitis mice." (PMID 33995942, 2021). "RG and fRG also alleviated the EC- or IS-induced colitis in mice; they suppressed the EC-induced myeloperoxidase activity, NF-κB activation, and TNF-α and IL-6 expression, and NF-κB+/CD11c+ cell population in the colon." (PMID 32224881, 2020). "The elevated level of inflammation cytokines IL-6, TNF-α, IFN-γ in colon, and LCN2 in feces and serum of colitis mice were decreased by miR-125a and miR-125b agomir injection." (PMID 32733020, 2020). "On the other hand, RES had no significant impact on MPO activity and levels of TNF-α, PGE2, IL-6 and IL-10 in mouse models of DSS-induced colitis." (PMID 32722619, 2020). "In the present study, we found that vidofludimus inhibited the expression of IL-17 and other inflammatory cytokines including IL-6 and IL-1β, as well as COX-2 in the intestine from DSS-induced colitis mice is dependent on the existence of FXR." (PMID 32477115, 2020). "Another polyphenol, Ellagic acid, shows similar effects by reducing the expression and production of IL-6 and TNF-α, and MAPK phosphorylation in colitis mice." (PMID 33664740, 2020). "The levels of IL-1β, IL-6, and TNF-α significantly increased after colitis was induced, and these levels were significantly reduced in the SASP, PCO, TCCO, and OO groups compared with the AA-alone group." (PMID 31936300, 2020). "In our results, we demonstrated that repeated EA intervention ameliorates DSS-induced colitis by suppressing proinflammatory mediators, including CRP, IFN-γ, TNF-α, and IL-6 through the TLR4 signaling via MyD88-dependent pathway." (PMID 32419794, 2020). "In TNBS-induced murine colitis, silymarin, has been shown to rebalance inflammatory cytokines such as TNF-α, IL-1β, and IL-6." (PMID 32486445, 2020). "To assess the protective effect of NZ9000SHD-5 on DSS-induced colitis, we evaluated the protein levels and gene expression of common pro-inflammatory cytokines TNF-α, IL-6, and IL-1β in colon tissue." (PMID 32122364, 2020). "In contrast, sinapic acid was shown to reduce the generation and mRNA expression levels of some inflammatory cytokines (TNF-α, IL-1β, IL-6, IL-8, IL-17α, and IFN-γ) and reduce the activation of the NLRP3 inflammasome in the colons of colitis mice." (PMID 33312339, 2020). "In the present study, increased production of iNOS, COX-2, IL-6, TNF-α, and IL-1β was observed in mice with DSS-induced colitis." (PMID 33536931, 2020). "Oral administration of boldine attenuates DSS-induced colitis and reduces colonic phosphorylation of STAT3 and NF-κB p65 subunit as well as the expression of TNFα, IL-6, and IL-17." (PMID 32855621, 2020).
colitis (continued). "The increased secretion of IL-1β, IL-6 and TNF-α has been demonstrated in experimental colitis models and in patients with IBD." (PMID 32971925, 2020). "Further research has shown that thalidomide can reduce the levels of TNF-α, IL-1, IL-6, MPO, and NO in TNBS-induced mouse colitis, in turn reducing the inflammatory response in CD." (PMID 32766176, 2020). "IL-6 binds to soluble or membrane-bound IL-6 receptors and triggers the activation of STAT3; STAT3 is highly phosphorylated in DSS-induced colitis in mice and human IBD patients." (PMID 32859970, 2020). "Inflammation-related factors (Il1b, Tnfa, Il6, Il17, and Inos) were analyzed at the mRNA level in the DSS colitis colon after receiving IFX delivery formulation." (PMID 32933548, 2020). "Similar to the results in the colitis model, the ultralow dose of DPI significantly decreased the plasma levels of IL-6 and TNF-α compared with those in the control group." (PMID 32550901, 2020). "We also observed that sinapic acid treatment significantly reduced the mRNA expression levels of TNF-α, IL-1β, IL-6, IL-8, IL-17α, and IFN-γ in the colons of colitis mice." (PMID 33312339, 2020). "At the same time, IL-6, IL-17A, IL-23, TNF-α, and TGF-β1 expressions were significantly decreased in colitis mice treated by SSP." (PMID 32581849, 2020). "During colitis, TWD increased expression of Tnf by 2.5-fold, Il1b by 2.8-fold, Il4 by 4.8-fold, Il6 by 3.3-fold, Ifng by 3.8, and Il17f by 4.2-fold as compared to mice fed the AIN diet." (PMID 32093192, 2020). "Colon tissues from the naive, colitis, Exo, IFN-γ Exo, and miRNA treated mice were collected for the detection of TNF-α, IFN-γ, and IL-6." (PMID 32733020, 2020). "It has been reported that an iridoid-rich fraction of Syringae folium extract possessed an anti-inflammatory effect against TNBS-induced colitis in rats through inhibiting proinflammatory cytokines (TNF-α, IL-6) by downregulating the expression of NF-κB." (PMID 33299531, 2020). "Pretreatment of colitis mice with L. reuteri I5007 significantly reduced the DSS-induced production of TNF-α, IL-6, IFN-γ, and IL-17A, as well as increased the level of IL-10 compared with the DSS group." (PMID 32751784, 2020). "Neutrally charged EPS from the putative probiotic Streptococcus thermophiles also decreased the production of the pro-inflammatory cytokines IFN-γ, IL-6, and TNF-α in DSS-induced colitis." (PMID 32351514, 2020). "Further, previous Korean study suggest the chelidonine ameliorates colon injury and inhibits the increase of inflammatory mediators, such as IL-6 and TNF-α, and oxidative damage in murine colitis model." (PMID 32612148, 2020). "The dramatically elevated mRNA expression levels of MCP-1, TNF-α, IL-6, IL-1β, and IFN-γ in the colon are important features of the DSS colitis model." (PMID 33042117, 2020). "Muscadine grapes or wine phytochemicals are capable to decrease MPO activity as well as colonic levels of IL-1β, IL-6, and TNF-α in experimental DSS-colitis." (PMID 32429359, 2020). "Intrarectal treatment of colitis with 30 mg/kg chitosan alone and with 30 mg/kg 5-ASA for 3 days led to a significant decrease in MPO, ALP, TNF-α, IL-6, IL-1β and NF-κB in colitis mice compared to untreated mice." (PMID 33138176, 2020). "Consistent with the results of a previous experiment, increased levels of the cytokines IL1α, TNF‐α, IL6, IL12P40 and MIP‐1A were observed in mice with DSS‐induced colitis." (PMID 32363766, 2020). "Although α7nAChR agonists reduced NF-κB transcriptional activity, IL-6 and TNF release, α7nAChR agonists worsened the effects of DSS-induced colitis or were ineffective in a model of TNBS-induced colitis." (PMID 32265899, 2020). "The results indicated that SSP inhibited pro-inflammatory factors (as IL-6, IL-17A, IL-23, and TNF-α) and improved IL-10 expression, or restrained TGF-β1 in the colonic tissue of colitis mice." (PMID 32581849, 2020).
colitis (continued). "Soy-derived isoflavones have previously prevented colitis in a murine model and reduced the mRNA levels of TNF-α, IL-1β, IL-6, iNOS, and COX-2." (PMID 32708415, 2020). "In a dextran-sulfate-induced colitis animal model, Yue and colleagues showed that the polysaccharides ameliorated the inflammatory response through lowering TNF-α, IL-1β, IL-6, and MPO activity and increased AMPK activity." (PMID 32560291, 2020). "KM1608 significantly attenuated the disease activity of dextran sodium sulfate-induced colitis in mice and suppressed inflammatory mediators such as myeloperoxidase, proinflammatory cytokines (TNF-α and IL-6), and the Th2-type cytokine IL-4 in the colon." (PMID 32927852, 2020). "It has been noted that the reduction in inflammatory cytokines, such as TNF-α, IL-6, IL-1β, IFN-γ, and IL-17A, in the serum represents a target for IBD therapy, as they play leading roles in the formation of colitis." (PMID 32751784, 2020). "Synergistically, Rg3-RGE + PT inhibited expression of NO, iNOS, COX-2, IL-1β, IL-6, IL-5, IL-13, and TNF-α in the DSS-induced colitis mice’s macrophage cells, plasma, and colon tissue." (PMID 33182623, 2020). "As pro-inflammatory factors, IL-6, IL-17A, IL-23, and TNF-α are classical hallmarks of colitis, which induce the occurrence of colitis." (PMID 32581849, 2020). "The level of inflammation cytokines TNF-α, IFN-γ, and IL-6 of the colon tissue and lipocalin-2 (LCN2) of feces and serum were significantly elevated in colitis mice." (PMID 32733020, 2020). "The mRNA levels of IL-1β, TNF-α, iNOS, IL-6, and iNOS were markedly increased in mice with DSS-induced colitis." (PMID 33536931, 2020). "The findings of the present study are indicative of the preventive ability of Cordia vignei leaf extract against the damaging effect of acetic acid-induced colitis in Sprague Dawley rats through inhibition of TNF-α and IL-6 activities." (PMID 32090060, 2020). "In a mouse model of colitis, CUR treatment decreased the expression of TNF-α, IL-2, IL-6, IL-12 p40, IL-17, and IL-21 to a level comparable to healthy mice." (PMID 32423101, 2020). "The levels of the proinflammatory cytokines IL1β, IL6 and TNF‐α are increased in both animal models of colitis and patients with UC." (PMID 32363766, 2020). "Our model showed that bacteria colonization induced elevated detection of Th1 pro-inflammatory cytokines INF-γ, IL-6, and TNF-α, which have been previously suggested to create an inflammatory loop and worsen colitis in mice." (PMID 32444671, 2020). "According to researchers, flavonoids suppressed the activation of TLR-4/NF-κB p65 signaling pathway, leading to a decrease in gene expression of TNF-α, IL-1B, and IL-6, COX-2, TFF-3, and iNOS proteins in the intestinal mucosa in colitis model." (PMID 32848723, 2020). "Treatment with rSj-Cys significantly reduced TNBS-induced experimental colitis in mice through upregulation of Treg cells and related cytokines IL-10 and TGF-β, and downregulation of pro-inflammatory cytokines TNF-α and IL-6 in the colon tissues of mice." (PMID 32423469, 2020). "Our study found that dietary TS ameliorated neutrophil accumulation in the colon of DSS-induced colitis mice which was accompanied with decreased TNF-α, IL-6, and IL-1β expression." (PMID 33363184, 2020). "In this study, we found that the serum levels of TNF-α, IL-1β, IL-6, IL-8, IL-17α, and IFN-γ in colitis mice were significantly decreased by treatment with sinapic acid." (PMID 33312339, 2020). "To gain insight into the effect of MMI-0100 on the DSS-induced colitis, we assessed a series of pro-inflammatory cytokines at mRNA levels, such as TNF-α, IL-6, IL-1β, TGF-β, IFN-γ, IL-17A, COX-2 and iNOS." (PMID 31382637, 2019). "Apple polyphenolic extracts, soy and sulforaphane flavonoid compounds reduce pro-inflammatory cytokine expression (IL-1β, TNF-α, IL-6, IL-17, and IFN-γ) in the context of a chemically induced colitis." (PMID 31031748, 2019).
colitis (continued). "Our results showed that IL-1β, IL-6, and IL-17A were all down-regulated in mice with DSS-induced colitis, following treatment with M2b macrophage exosomes." (PMID 31749791, 2019). "B. adolescentis IF1-03 stimulated macrophage maturation to produce higher levels of IL-10 and lower levels of IL-6 and TGF-β, consistent with the upregulation of Treg cells in DSS-colitis mice in vivo, and splenocytes in vitro." (PMID 30987344, 2019). "Induction of colitis and JGT treatment changed compositions of gut microbiota and inflammatory cytokine levels (TNF-α and IL-6)." (PMID 30800169, 2019). "It confirms that CRHR2 receptor antagonists (Astressin2B) can block the TLR4/NF-κB signaling pathway in DSS-induced colitis mice to reduce the levels of TNF-α, IL-6, and IL-1β in serum, thereby protecting the colon mucosa." (PMID 30881446, 2019). "Further, another study reported that Astragalus reduced NF-κB DNA phosphorylation activity and decreased the levels of TNF-α, IL-6, and MPO activity in the setting of colitis." (PMID 30610157, 2019). "Treatment of UC with SP, honey, and combination regimen significantly reduced TNF-α, IL-1β, IL-6, MDA, MPO, NO, and PGE2, and increased TAC, GSH, GPx, and SOD in interventional groups compared to the AA-colitis group (P<0.05)." (PMID 34466462, 2019). "Surprisingly, levels of IFN-γ were highly elevated; other proinflammatory cytokines were elevated, including TNF- α and IL-6, suggesting that OVA-induced colitis is mediated through Th1 responses." (PMID 30949176, 2019). "Consistent with increased access of these pro‐inflammatory factors, serum levels of IL‐1β, TNF‐α and IL‐6 were elevated in DSS‐treated mice, which were drastically reduced in mice colitis model following CHC treatment." (PMID 31418947, 2019). "During the pro-inflammatory response of colitis among others, NF-κB drives the expression of TNF-α and IL-6." (PMID 31010141, 2019). "Intratracheal OVA-induced colitis resulted in production of T-bet mediated cytokines, including TNF-α, IL-6, and IFN-γ in normal mice, while OVA exposure of T-bet deficient mice failed to result in induction of colitis." (PMID 30949176, 2019). "The ethanol extract of CBR, a product of A. camphorata grown on GBR, improved DSS-induced colitis in mice and this effect was attributed to the reduction in iNOS, COX-2, TNF-α and IL-6." (PMID 31717536, 2019). "GAL administration in DSS colitis in mice induced an increased level of anti-inflammatory cytokines (IL-10) and decreased levels of pro-inflammatory mediators (TNF, IL-6, and iNOS)." (PMID 31434263, 2019). "Our previous work has investigated the protective effects of tryptanthrin on colitis, which was closely related to TNF-α/NF-κB and IL-6/STAT3 pathways." (PMID 31726738, 2019). "Oral administration of AL-1 significantly attenuates the production of IL-1β, IL-6, TNF-α, PGE2, and IFN-γ in the sera of colitis mice." (PMID 31687082, 2019). "In summary, our findings show that M2b macrophage exosomes attenuate disease activity, up-regulate Treg cells and IL-4, and reduce pro-inflammatory cytokine (IL-1β, IL-6, and IL-17A) production in mice with DSS-induced colitis." (PMID 31749791, 2019). "Colitis induction increased serum IL-6, TNF-α, and IL-1β by 5-, 4.25-, and 1.9-fold, respectively in AA-colitis group in comparison to the NC group." (PMID 34466462, 2019). "In the experimental colitis model, activated DCs produce numerous pro-inflammatory cytokines including TNF-α, IL-1β, IL-6, and IL-12 and express high levels of co-stimulatory molecules including CD80 and CD86." (PMID 31286993, 2019). "In a colitis rat model, the number of ulcers, pathological scale, and TNF-α, IL-1β, and IL-6 levels were reduced following treatment with KJL." (PMID 31534467, 2019). "Our present results showed that colonic IL-6 levels were decreased in orange pectin-fed mice both in TNBS- and DSS-induced colitis." (PMID 31921214, 2019).